AHNAK (AHNAK nucleoprotein)
Diseases named in the same sentence as AHNAK in open-access papers (continued):
Sharing a sentence is not in itself a finding about the gene and the disease.
cancer (59 papers, 2013 to 2025). A tumor composed of atypical neoplastic, often pleomorphic cells that invade other tissues. "AHNAK is a large scaffolding protein that has been linked to migration and invasion in other cancers." (PMID 33564071, 2021). "AHNAK has been implicated in cancer progression although its functional role is controversially discussed." (PMID 31320997, 2019). "In some instances, the identified genes have already been shown a potential value for assessing response to cancer treatment, such as neuroblast differentiation-associated protein (AHNAK) and H2A histone family, member X (H2AX)." (PMID 26089344, 2015). "In addition, AHNAK mutation was considered as a prognostic factor associated with poor survival of patients with different cancers." (PMID 34922552, 2021). "All germline AHNAK mutations were also present in cancer samples from those same patients." (PMID 32373223, 2020). "Using univariate regression analysis, we examined the associations of AHNAK and AHNAK2 with the prognosis of 33 cancers by R language." (PMID 38033502, 2023). "Unfortunately, the role of AHNAK in all cancer types reported in three or more studies has been somewhat controversial." (PMID 38033502, 2023). "Contribution of the expression of AHNAK to survival by univariate Cox regression analysis in cancers." (PMID 38033502, 2023). "AHNAK is a cancer inhibitor protein and inhibits the developmental process of mammary and pulmonary cancer via enhancing the transforming growth factor-β (TGF-β) signal path." (PMID 36211359, 2022). "Interestingly, AHNAK has been implicated in the regulation of cell membrane cytoarchitecture, as well as pseudopod protrusion via interaction with Annexin A2, septin-9, and Ca2+-dependent S100 proteins, which have both been shown to contribute to cancer metastasis." (PMID 33564071, 2021). "Aside from migration, AHNAK has also been shown to regulate proliferation of several cancers and enhances the PKCα signaling pathway in fibroblast which coincides with our RNA-seq data." (PMID 33564071, 2021). "In recent years, there has been increasing interest in understanding the function of AHNAK in various malignant tumours." (PMID 28494797, 2017). "AHNAK, also known as desmoyokin, is a giant protein with the molecular size of approximately 700 kDa and exerts diverse functions in different types of cancer." (PMID 28494797, 2017). "So far, it has been demonstrated that the expression of AHNAK is variable in different types of cancer." (PMID 28494797, 2017). "By quantifying cancer genome evolution using the gene gravity model, we identified six putative cancer genes (AHNAK, COL11A1, DDX3X, FAT4, STAG2, and SYNE1)." (PMID 26352260, 2015). "Most importantly, our study is the first to identify AHNAK as a potential prognostic marker in cancer." (PMID 23409183, 2013). "AHNAK plays a suppressive or progressive role in different types of cancers." (PMID 36557813, 2022). "Besides, the proliferation rate of cancer cells was significantly decreased after AHNAK and NFATC1 knockdown." (PMID 35958586, 2022). "Based on these observations, AHNAK might be a multifunctional protein and play variable roles in different types of cancers." (PMID 36557813, 2022). "The aberrant expression of AHNAK has been reported in various cancer." (PMID 35027921, 2021).
cancer (continued). "Moreover, studies have recently found that AHNAK is pivotal in cell migration along with infiltration in an extensive range of cancers." (PMID 34689136, 2021). "AHNAK is a calcium transporter known to be involved in cancers and CVDs." (PMID 32425973, 2020). "AHNAK is a giant protein which exerts diverse functions in different human cancers." (PMID 32733809, 2020). "No details about AHNAK2 function are available, but its closest relative AHNAK is involved in cancer migration and EMT, providing support that AHNAK2 may elicit similar features." (PMID 26993610, 2016). "The role of AHNAK in cancer is poorly characterized at present." (PMID 23409183, 2013). "Moreover, AHNAK also correlated with the progression, migration, and invasion of cancers." (PMID 33456631, 2020). "However, mutations of AHNAK have not been studied in the context of the immune response in cancer, and our report describes for the first time an association with outcome and immune cell recruitment in the immune response setting against basal-like tumors." (PMID 32796628, 2020). "Expression validation in the transcriptome, TCGA–BLCA, and GSE13507 datasets confirmed the up-regulation of APOL1, DHX34, and TNK2, and the down-regulation of AHNAK, CSPG4, NCAM1, and PCDHB4 in the cancer group." (PMID 40908816, 2025). "It turned out that AHNAK and AHNAK2 were significantly differentially expressed in cancer and paraneoplastic tissues of some tumors." (PMID 38033502, 2023). "Similar to AHNAK, STAP1 methylation was also related to alcohol drinking, which suggests that these bad habits do affect the occurrence of cancer." (PMID 36713363, 2022). "It has been suggested that AHNAK plays an inhibitor role in migration and invasion, as well as EMT in cancer." (PMID 34198846, 2021). "The results revealed that both RNF38 and AHNAK were present in the cytoplasm of HCC cells, and that positive TGFBR1 staining was mainly localized in the membrane and cytoplasm of cancer cells." (PMID 30836988, 2019). "Finally, the enhanced crosslinking and immunoprecipitation (eCLIP) analyses reveal that FXR1 binds with the G4-enriched mRNA targets such as AHNAK, MAP1B, AHNAK2, HUWE1, DYNC1H1 and UBR4 and controls its mRNA expression in cancer cells." (PMID 38709899, 2024). "In this study, AHNAK showed hypomethylation and increased expression in HCC, suggesting that AHNAK may act as a cancer promoter." (PMID 38033502, 2023). "AHNAK was found to promote TGFβ/SMAD3-induced EMT and cancer metastasis." (PMID 35158796, 2022). "One limitation is, for instance, the fact that other functions of AHNAK in cancer and its relevance to the current research are not described: for example, the role of AHNAK in EMT." (PMID 34689136, 2021). "In addition, we found in this list established cancer genes involved in other types of cancer, such as PDE4DIP, SF3B1, AHNAK, COPB2, CSDE1, KIF5B, NDUFA10, RSRC2." (PMID 31949199, 2020). "A potential role of AHNAK as prognostic marker for survival in cancer patients has, however, never been shown thus far." (PMID 23409183, 2013). "For early-stage cancers, DNA methylation-based biomarkers are of particular importance Recent scientific work indicates the high potential of hypermethylated genes TWIST1, VIM, ZNF671, OTX1, and IRF8 for early diagnosis and PTK2, AHNAK, and DAPK for BC prognosis." (PMID 39685620, 2024). "The cancer-promoting AHNAK expressed in HCC field cancerization might be a new opportunity worthy of study to explore the signature of HCC field cancerization and to comprehend the important role that AHNAK plays in HCC development and progression." (PMID 36557813, 2022).
infection (4 papers, 2019 to 2025). The state of being infected such as from the introduction of a foreign agent such as serum, vaccine, antigenic substance or organism. "Interestingly, AHNAK phosphorylation at S210 was also regulated during infection of Calu-3 cells with early-lineage or Alpha variant SARS-CoV-279,80." (PMID 37758692, 2023). "This function is important in pathogen infection with bacterium Salmonella, where AHNAK is recruited to membrane ruffles and is required for infection." (PMID 37758692, 2023). "TmeA interacts with host AHNAK, but infection of AHNAK-deficient cells does not affect invasion or intracellular growth." (PMID 40996286, 2025). "Together, our data pinpoints how molecular regulation of AHNAK in response to infection could be reflective of the systemic effect of AHNAK as it relates to disease severity in the host." (PMID 37758692, 2023). "The additional layer of phosphoregulation during IAV infection for IAV-human PPIs, including PRKDC and AHNAK, may highlight increased functional importance of the interaction in infection." (PMID 37758692, 2023). "Moreover, a C. trachomatis tmeA mutant shows a defect in host cell invasion regardless of the cells being AHNAK-positive or AHNAK knocked-out, and there is no defect in invasion associated with infection of AHNAK knocked-out cells by wild-type C. trachomatis." (PMID 31528632, 2019). "Of our identified host factors, 54 significantly alter IAV infection upon siRNA knockdown, and two factors, AHNAK and coatomer subunit COPB1, are also essential for productive infection by SARS-CoV-2." (PMID 37758692, 2023). "Three of these IAV host factors also regulate infection by SARS-CoV-2, acting as pro-viral (COPB1, AHNAK) or antiviral (RUVBL2) factors of SARS-CoV-2 infection." (PMID 37758692, 2023). "Our study uniquely identifies AHNAK as essential for SARS-CoV-2 infection, perhaps through AHNAK’s interaction with viral RNA that may play a critical role in viral RNA production, trafficking or assembly during infection." (PMID 37758692, 2023).
neurodevelopmental disorder (1 paper, 2022). A behavioral and cognitive disorder with onset during the developmental period that involves impaired or aberrant development of intellectual, motor, or social functions. "In recent studies, the AHNAK gene, a multifunctional protein in the brain, was found to be one of the neurodevelopmental disorder risk genes, potentially modulating depressive behavior." (PMID 36292679, 2022).
AHNAK also shares sentences with these, for which no sentence is quoted: triple-negative breast carcinoma (5 papers); colorectal cancer (4); bladder urothelial carcinoma (2); acute lymphocytic leukemia (1); adrenocortical carcinomas (1); allergic rhinitis (1); amelanotic melanoma (1); Arrhythmia (1); Autoimmunity (1); bacterial infection (1); bipolar disorder (1); brain tumor (1); chronic hepatitis B (1); Cirrhosis (1); clear cell renal cell carcinoma (1); connective tissue diseases (1); dermatomyositis (1); diabetes (1); dystrophinopathy (1); endothelial dysfunction (1); esophageal cancer (1); glaucoma (1); hepatitis B (1); hereditary hemochromatosis (1); Impaired glucose tolerance (1); long QT syndrome (1); lymphopenia (1); medulloblastoma (1); metabolic disease (1); metabolic syndrome (1).
A further 15 diseases each share a sentence with AHNAK in 1 paper.